MIR7152 (microRNA 7152)
Synonyms: hsa-mir-7152
Gene: MicroRNA gene on chromosome 10 (71,790,747 to 71,790,800, forward strand). Ensembl gene ENSG00000274824.
Homologues: Orthologues: chimpanzee MIR7152 (100% identical).